MIR4506 (microRNA 4506)
Synonyms: hsa-mir-4506
Gene: MicroRNA gene on chromosome 14 (93,948,226 to 93,948,302, reverse strand). Ensembl gene ENSG00000265768.
Homologues: Orthologues: chimpanzee MIR4506 (100% identical).